MMP1 (matrix metallopeptidase 1)
Diseases named in the same sentence as MMP1 in open-access papers (continued):
Sharing a sentence is not in itself a finding about the gene and the disease.
invasive breast carcinoma (8 papers, 2012 to 2025). A carcinoma that infiltrates the breast parenchyma. "Elevated expression of matrix metalloproteinase 1 (MMP1) has been associated with poor disease-free survival (DFS) and OS in patients with invasive breast carcinoma." (PMID 40287412, 2025). "High MMP-1 gene expression has also been reported to predict for a lower overall survival rate in invasive breast carcinoma and poorer prognosis in patients treated with systemic therapy; thus, the expression of MMP-1 is a significant prognostic indicator and a potential drug target for BC." (PMID 34445715, 2021). "High MMP1 expression might predict poor disease-free and overall survivals in patients with invasive breast carcinoma." (PMID 28334049, 2017). "In addition, some studies also found that high MMP1 expression might predict poor disease-free and overall survivals in patients with invasive breast cancer." (PMID 28334049, 2017). "However, expression of EGFR and MMP-1 demonstrate a significant trend towards co-occurrence (p < 0.001), suggesting that this pathway may be maintained in invasive breast cancers." (PMID 26215578, 2015). "Likewise, MMP1 expression in immune cells surrounding cancer cells in positive sentinel nodes was also strongly associated with tumor involvement of non-sentinel lymph nodes in patients with invasive breast cancer." (PMID 33396463, 2020). "Expression of MMP-1 was found to be higher in atypical ductal hyperplasia (ADH) from patients that progressed to invasive breast cancer than those from patients that did not progress." (PMID 26215578, 2015). "Higher MMP1 expression could predict worse disease-free survival (DFS) and OS in patients with invasive breast cancer, but the mechanism underlying this association is not clear." (PMID 35037689, 2022).
ischemic stroke (8 papers, 2011 to 2026). A stroke disorder caused by obstruction of blood flow to the brain, due to thrombotic (local blood clot formation) or embolic (due to a blood clot or other material traveling from another site) event. "This review will evaluate the evidence for associations between polymorphisms in MMP-1, 2, 3, 9, and 12 with ischemic stroke incidence, pathophysiology, and clinical outcome." (PMID 27529234, 2016). "It found that lower serum levels of MMP-12 were associated with an increased risk of ischemic stroke, lower serum levels of MMP-1 and MMP-12 were linked to an increased risk of large-artery stroke, and higher serum levels of MMP-8 were associated with an increased risk of small vessel stroke." (PMID 38697862, 2024). "The first study examined the causal effects of MMP-1, MMP-8, and MMP-12 levels on ischemic stroke." (PMID 38697862, 2024). "pGSN is cleaved in vitro by MMP-3, MMP-2, MMP-1, MMP-14 and MMP-9 which may be the cause of the severe depletion of pGSN observed in patients who suffer ischemic stroke." (PMID 22047744, 2011). "The 21 ischemic stroke genes overlapping with genes that code for ECM-related proteins included COL3A, MMP1, MMP12 and MMP3." (PMID 33730931, 2021).
lung disease (8 papers, 2014 to 2024). "The peroxisome proliferator-activated receptor (PPAR) signaling pathway was the most enriched pathway associated with lung disorders, and matrix metalloproteinase-1 (MMP-1) in this pathway was mutually exclusive with several genes in IPF and NSCLC." (PMID 33046043, 2020). "Diseases associated with MMP1 include epidermolysis bullosa dystrophica, ar and pulmonary disease, chronic obstructive." (PMID 27906043, 2016). "This means that in our study population MMP-1 and -12 levels in itself carry information about clinical pulmonary disease and subclinical vascular disease even when accounting for traditional risk factors especially smoking habits." (PMID 30789935, 2019). "On the other hand, MMP1 had its unique mutually exclusive partners in IPF and NSCLC, respectively, and had high coverages for all these lung disorder types." (PMID 33046043, 2020). "Pentadecanoylcarnitine also had dose-dependent tissue remodeling activities in two cell systems relevant to lung disease, fibrosis, and wound healing, including lowered plasminogen activation inhibitor 1 (PAI-1), matrix metallopeptidase 1 and 9 (MMP1, MMP9), and tissue plasminogen activator (tPA)." (PMID 35999445, 2022).
endothelial dysfunction (7 papers, 2009 to 2025). In vascular diseases, endothelial dysfunction is a systemic pathological state of the endothelium (the inner lining of blood vessels) and can be broadly defined as an imbalance between vasodilating and vasoconstricting substances produced by (or acting on) the endothelium. "Carrizzo and coworkers have shown that PTX3 promotes endothelial dysfunction and morphological changes by a mechanism dependent on P-selectin and matrix metalloproteinase-1 (MMP1) pathway." (PMID 31354697, 2019). "Moreover, inhibition of MMP1 protected mesenteric arteries against the endothelial dysfunction promoted by PTX3, an effect absent in P-selectin-deficient mice." (PMID 31354697, 2019). "Endothelial dysfunction was observed in PA-treated HAECs, including impaired total antioxidant capacity, cell viability, NO levels, and eNOS, MFN2 and UQCRC1 protein levels, as well as significant up-regulation of IL6, MMP1, and CHOP mRNA levels." (PMID 37237885, 2023). "Tryptase activates metalloproteinases (MMP), such as MMP-1, MMP-2 and MMP-3 and procollagenase, and promotes the degradation of lipoproteins and fibronectin, acting as powerful inflammatory stimulus at the endothelial dysfunction." (PMID 26038676, 2015).
esophageal adenocarcinoma (7 papers, 2010 to 2021). A malignant tumor with glandular differentiation arising predominantly from Barrett mucosa in the lower third of the esophagus. "ERK MAP kinase signaling is an important driver of PEA3-mediated transactivation and downstream MMP-1 expression in oesophageal adenocarcinoma-derived cell lines." (PMID 21143918, 2010). "Besides that, miR-330-5p repressed cell invasive phenotype through downregulating MMP1 expression in esophageal adenocarcinoma." (PMID 34158077, 2021). "Although our study did not reveal correlation between MMP3–1612 6A/5A, MMP12 -82A/G polymorphisms and RHD in Han population, studies have shown a combined effect of MMP1–1607 1G/2G, MMP3–1612 6A/5A and MMP12-82A/G polymorphisms associated with esophageal adenocarcinoma (EA) risk in Caucasian." (PMID 29458338, 2018). "In oesophageal adenocarcinoma-derived OE33 cells, depletion of PEA3 leads to a reduction in the expression of MMP-1, an important player in metastasis and reduced invasion." (PMID 21143918, 2010). "To establish whether PEA3 subfamily members might also play a role in controlling MMP expression in human cancers, we determined the levels of MMP-1 and MMP-7 mRNA expression in tissue samples from patients with oesophageal adenocarcinomas." (PMID 21143918, 2010).
knee osteoarthritis (7 papers, 2018 to 2023). "Our findings also indicated that the high protein level of MMP-1 in the cartilage tissue might be linked to the high knee osteoarthritis risk in the Chinese population." (PMID 33331536, 2020). "An extract of FDR reduced the expression of caspase-1, caspase-3, caspase-9, and matrix metallopeptidase-1 (MMP-1) in articular cartilage of a rabbit knee osteoarthritis model, which reduced cartilage damage and had an osteoprotective effect." (PMID 36950009, 2023).
metastatic cancers (7 papers, 2012 to 2025). A carcinoma which has spread from the original site of growth to another anatomic site. "Elevated MMP1 levels are often upregulated in metastatic cancers, including uveal melanoma, where they are associated with an aggressive tumor phenotype and poor prognosis." (PMID 40004863, 2025). "This activation would result in enhanced matrix metallopeptidase 1 (MMP1)—a critical protease for metastatic cancer and thereby cancer progression." (PMID 33113804, 2020). "Our results, together with those from many other studies, suggest that blocking the actions of MMP-1 should theoretically prove beneficial in the treatment of invasive and metastatic cancers." (PMID 23217186, 2012). "These included genes which are implicated in inflammation and inflammatory responses to cancer (PTX3, IL8, TNFSF10, SERPINB13 and ANKRD1) and those involved in cell adhesion, cell migration and ECM degradation of importance in metastatic cancer (MMP12, MMP1 and ADAM19)." (PMID 28555042, 2017). "Understanding how MMP-1 and other members of the MMP family promote metastasis, in part by altering the signaling milieu in the tissue microenvironment colonized by disseminating cells may be crucial for developing more effective therapies for metastatic cancer." (PMID 23217186, 2012).
nasal polyps (7 papers, 2014 to 2024). "Previous studies have demonstrated increased expression of MMP-1, -2, -3, -7, -8, and -9 in the nasal polyp tissues of patients with CRSwNP, and upregulation of MMP-9 expression in CRSwNP is widely reported." (PMID 37176151, 2023). "Previously, TLR4 activation by LPS leads to increased MMP-1 expression in small airway cells and nasal polyp-derived fibroblasts." (PMID 33199767, 2020). "Our study revealed that TLR4 is important for the production of pro-inflammatory cytokines and MMP-1 in nasal polyp organ cultures." (PMID 25390332, 2014). "To confirm the inhibitory effect of TLR4 antagonist on production of IL-6, IL-8, and MMP-1 in human tissues, we cultured nasal polyp organ cultures and treated the cells with LPS in the presence or absence of LPS-RS." (PMID 25390332, 2014). "In this study, we explored the role of TLR4 in gene expression of immune responses leading to IL-6, IL-8, and MMP-1 production after LPS stimulation in nasal polyp." (PMID 25390332, 2014). "MMP-1 protein was primarily localized at the basement membrane and expressed in the cytoplasm of fibroblasts and inflammatory cells of nasal polyp tissue." (PMID 25390332, 2014). "Our data confirm that MMP-1 expression is increased in nasal polyp tissues compared to inferior turbinate tissues." (PMID 25390332, 2014). "In a recent study, MMP-1 expression was shown to be significantly increased in nasal polyps and CRS compared with normal nasal mucosa." (PMID 25390332, 2014). "The protein expression level of MMP-1 increased in nasal polyp tissues compared to inferior turbinate tissues." (PMID 25390332, 2014). "Western blot analysis showed that MMP-1 protein expression levels increased in nasal polyp tissues compared to inferior turbinate tissues." (PMID 25390332, 2014). "Additionally, we found that expression of IL-6, IL-8, and MMP-1 is stimulated by LPS via TLR4 in nasal polyp organ cultures." (PMID 25390332, 2014). "Previous studies provided evidence for higher levels of MMP‐1, MMP‐2, MMP‐3, MMP‐7, MMP‐8, and MMP‐9 in nasal polyps." (PMID 34504680, 2021). "We showed that LPS induces MMP-1 gene expression and collagenase activity and activates the ERK and p38 MAPK pathways in nasal polyp-derived fibroblasts." (PMID 25390332, 2014). "To examine MMP-1 protein expression, we compared MMP-1 expression level in inferior turbinate and nasal polyp tissues." (PMID 25390332, 2014). "Our results suggest that IL-25-induced release of α-SMA, fibronectin, collagen, MMP-1 and MMP-13 from NPDFs is mediated by the combined activation of the MAPK and NF-kB pathways, thereby providing new clues for fibroblast-mediated inflammation by changing the ECM composition in nasal polyps." (PMID 28771607, 2017).
oesophageal cancer (7 papers, 2010 to 2024). "An analysis of The Cancer Genome Atlas (TCGA) database revealed that MMP1 was esophageal carcinoma, pancreatic adenocarcinoma, lung squamous cell carcinoma and significantly upregulated especially in HNSCC samples across all tumor samples and paired normal tissues." (PMID 38320998, 2024). "We have demonstrated that PEA3 family members control MMP-1 expression in oesophageal cancer cells." (PMID 21143918, 2010). "The upregulated expressions of MMP1 and MMP7 with miR-330-5p silencing were of particular interest because MMP1 and MMP7 have previously been reported as prognostic markers in oesophageal cancer." (PMID 31391080, 2019). "Through the integration of data information, it was found that the variable shear factor QKI was closely related to the epithelial mesenchymal transformation (EMT) of oesophageal cancer, and QKI might promote the EMT process by activating the expression of IL-11, MFAP2, MMP10 and MMP1." (PMID 37428781, 2023). "Several studies showed that MMP1 and MMP8 expressions were also elevated in esophageal carcinoma cells; however, these studies did not mention the effect of Arecoline on the muscarinic acetylcholine receptor." (PMID 30925742, 2019).
rotator cuff tear (7 papers, 2015 to 2025). "Consistent with this, clinical studies report that both MMP-1 levels are significantly higher in patients with rotator cuff tears and that their upregulation is tightly linked to healing failures." (PMID 40728980, 2025). "Another study concluded that genetic polymorphisms in MMP-1 and MMP-3 were associated with rotator cuff tears." (PMID 36833294, 2023). "Two studies found similar correlations between increasing expression/representation of VEGF, MMP-1, and -9 and increasing extent of a full-thickness rotator cuff tear, but these findings were not statistically significant." (PMID 25879758, 2015).
synovitis (7 papers, 2006 to 2025). Inflammation of a synovial membrane. "Inflammatory markers such as IL‐1β, IL‐6, TNF‐α and MMP1 increased with synovitis or severe chondral damage." (PMID 40989937, 2025). "In patients with grade 3 cases of synovitis, the levels of TNFα, IL1β, IL6, and MMP1 were significantly increased compared with those in cases of grade 2 synovitis (p < 0.05)." (PMID 28425031, 2017). "In the present study, the level of MMP1 was significantly higher in the synovial membrane of patients with diffuse synovitis, than in those with focal synovitis, suggesting that severe synovitis can progress to catabolic chondral degeneration via MMP1, which is mediated by TNFα and IL1β." (PMID 28425031, 2017). "A previous report has indicated that FA had the ability to decrease the levels of hydrogen peroxide-induced IL-1β, TNF-α, MMP-1, and MMP-13, thereby reducing bone destruction, synovitis, and the erosion of cartilage in antigen-induced arthritis." (PMID 24883069, 2014). "Immunohistochemical studies have found that, particularly in early OA, this synovitis has a mononuclear cell infiltrate, with considerable production of proinflammatory cytokines like TNF-α and IL-1β and destructive enzymes like MMP-1 and MMP-3." (PMID 17177994, 2006).
thyroid cancer (7 papers, 2014 to 2025). "Another network pharmacology study highlighted quercetin as a thyroid cancer treatment, with high binding affinity to modulators including MMP-1, C-X-C motif chemokine ligand-8, MMP-3, and collagen type 1 ꭤ1." (PMID 41226537, 2025). "PLAU and MMP-1 primarily mediate the prometastatic activity of NF-κB in thyroid carcinomas, given that they are involved in cancer cell migration and invasion, especially in advanced thyroid malignancies." (PMID 39519020, 2024). "Human thyroid carcinoma tissue has also been reported to express MMP-1, MMP-2, and MMP-9 and these MMPs were localized in tumor cells and/or in the fibroblasts adjacent to or close to the invading tumor cells." (PMID 36551933, 2022). "MMP1 has been reported to function as an oncogene in various cancer types, including thyroid cancer." (PMID 32982961, 2020). "At 400 uM, quercetin reduced thyroid cancer cell viability, MMP-1 and MMP-3 expression in vitro." (PMID 41226537, 2025). "They considered this finding to be related to MMP-1’s role in the invasion of thyroid cancer." (PMID 36551933, 2022). "Moreover, MMP1 is known to play a crucial role in many cancers' progression, including thyroid cancer." (PMID 32982961, 2020). "Proteomic studies on PTC tissue from humans have suggested NTRK1, metalloproteinases (MMP-1, MMP-9 and MMP-13) and Cathepsins (-W and -X), NF-KB and other apoptosis associated proteins as radiation-induced PTC biomarkers, together with SPANXA as an important protein for thyroid cancer development." (PMID 33382739, 2020).
type 2 diabetes (7 papers, 2007 to 2025). "On the other hand, MMP1 serum levels have been shown to be significantly increased in patients with type 2 diabetes." (PMID 37445827, 2023). "MMP expression in Type 2 diabetes LDL treated cells was significantly higher compared to control LDL treated cells for a] MMP-1 after 4 and 8 hours at all LDL concentrations, and b] MMP – 9 at 4, 8 and 24 hours at most LDL concentrations." (PMID 17714581, 2007). "In vitro, Type 2 diabetes LDL promoted the expression of the MMP-1, MMP-9, ADAM28, ADAM17 and ADAM15 genes compared to control LDL." (PMID 17714581, 2007). "Despite these limitations, these data suggests that LDL from subjects with Type 2 diabetes promotes increased monocyte mRNA expression of MMP-1, MMP-9, and ADAM proteinases responsible for inflammatory cytokine and adhesion molecule shedding." (PMID 17714581, 2007). "Type 2 diabetes is associated with increased APOE, BAX, MMP1, NFKB1, PDGFB, SPP1, and TGFB2." (PMID 35153741, 2021).
ulcers (7 papers, 2011 to 2024). "Gene analysis results confirmed that expression changes occurred in genes of key regulators of wound healing, such as chemokines, MMP-1, 9, CSF-2, and IL-33, and that such genetic changes enhanced wound healing in ulcers." (PMID 37508509, 2023). "Previous study showed MMP-1 concentration is significantly higher in H. pylori-induced ulcers compared to NSAID-induced ones." (PMID 22645431, 2012). "Particularly, all the collagenases (MMP-1, MMP-8 and MMP-13) are co-expressed, which have been shown to play roles of collagenases in wounds and ulcers." (PMID 35444067, 2022). "Non-healed ulcers exhibit elevated levels of MMP-1, -2, -8, and -9, while showing lower levels of TIMP-1." (PMID 38254696, 2024).
aortic aneurysm (6 papers, 2009 to 2022). A ruptured aneurysm located in the wall of the proximal portion of the descending aorta proceeding from the arch of the aorta. "We recently generated transgenic rabbits expressing human MMP-1 in a macrophage lineage and found that increased MMP-1 expression played a functional role in aortic aneurysm formation (Niimi and Fan, unpublished data)." (PMID 30413026, 2018). "Elevated MMP-1 and MMP-2 have been strongly associated with ruptured atherosclerotic plaques and aortic aneurysms." (PMID 28676082, 2017). "The levels of MMP-1 were found to be lower in healthy individuals compared to patients with acute and chronic aortic dissection, aortic aneurysm and myocardial ischemia." (PMID 19886986, 2009). "In agreement with this, several studies reported an increased expression and activity of MMP-1, MMP-2, MMP-3, MMP-9, and MMP-12 in aortic aneurysm tissues." (PMID 35456498, 2022). "Therefore, MMPs, especially MMP1 and MMP9, have been widely considered critical factors in the initiation and development of aortic aneurysms." (PMID 33029260, 2020).
astrocytoma (6 papers, 2018 to 2025). "MMP-1, also called interstitial collagenase, shows an especially significant overexpression of mRNA and proteins in astrocytomas characterized by a high degree of malignancy." (PMID 36291686, 2022). "The influence of CAPE on the secretion of cytokines (IL-8, IL-10, IL-26), metalloproteinases (MMP-1, -2, -3), and pentraxin-3 (PTX3) was assessed in CCF-STTG1 astrocytoma cells stimulated with LPS and/or IFN-α under normoxic and hypoxic conditions." (PMID 41515435, 2025).